ENSG00000288711 (novel protein)
Gene: Protein-coding gene on chromosome 21 (34,511,122 to 34,614,913, reverse strand). Ensembl gene ENSG00000288711.
Genetic constraint (gnomAD): Missense variants: 189 observed, 183.46 expected, observed/expected ratio (o/e) 1.03, 90% interval 0.91 to 1.16. Synonymous variants: 86 observed, 77.4 expected, observed/expected ratio (o/e) 1.11, 90% interval 0.93 to 1.33.